FCN2 (ficolin 2)
Diseases named in the same sentence as FCN2 in open-access papers (continued):
Sharing a sentence is not in itself a finding about the gene and the disease.
cancer (9 papers, 2012 to 2024). A tumor composed of atypical neoplastic, often pleomorphic cells that invade other tissues. "Low concentration of ficolin-2 was shown to confer a higher risk of liver cirrhosis and cancer in patients with chronic HBV infection." (PMID 35326694, 2022). "In conclusion, the characteristic high systemic/low local ratio of ficolin-2 and ficolin-3 in ovarian and possibly other carcinomas warrants further investigation to explain these associations." (PMID 23744477, 2013). "However, increased serum ficolin-2 was associated with the cancer patients (median 3.1 μg/ml; p < 0.000001 compared with C group)." (PMID 23744477, 2013). "A pan-cancer study centered on HCC-related molecular analysis was also conducted to look for a link between FCN2 and immune infiltration, immune modulators, and chemokine receptors." (PMID 36425563, 2022). "Subsequently, a series of analyses were carried out on FCN2, such as pan-cancer analysis, differential expression analysis, clinicopathological analysis, and immune infiltration analysis." (PMID 36425563, 2022). "The Oncomine database was used to examine the expression of FCN2 mRNA in various cancers and normal clinical samples." (PMID 36425563, 2022). "This was connected to the HCC marker alpha-fetoprotein, showing that FCN2 is involved in the development and progression of cancer." (PMID 36425563, 2022). "For example, ficolin-2 can interact with β-1,3 glucan, and β-1,3 glucans are being investigated as potential anti-cancer therapy agents (reviewed by Vetvicka)." (PMID 23744477, 2013). "Moreover, FCN2 also contributes to rheumatic and premature delivery as well as different kinds of cancers." (PMID 39739972, 2024). "The expression data of FCN2 in pan-cancer can be procured from the BioGPS database." (PMID 36425563, 2022). "Furthermore, the ovarian expression (at both mRNA and protein level) of FCN2 and FCN3 (ficolin-2 and ficolin-3, respectively) were lower in tissue sections from malignant tumours compared with benign tumours or normal ovaries." (PMID 35326694, 2022). "The FCN2-related pan-cancer analyses were designed to describe the immune effects of FCN2 and are critical in identifying cancer types that may benefit from FCN2-related immunotherapy." (PMID 36425563, 2022). "Consequently, high serum ficolin-2 (>2.9 μg/ml) concentrations were more frequent in cancer patients." (PMID 23744477, 2013). "Our experimental evidence and the meaningful correlation with AFP support the finding that FCN2 is underexpressed in HCC and that it has prognostic value in this cancer type." (PMID 36425563, 2022).
bacterial infections (6 papers, 2012 to 2020). "The FCN2 exon 8 +6359 C>T polymorphism has arisen as an important SNP involved in susceptibility to bacterial infections, especially following organ transplants." (PMID 30868077, 2019). "Genetic variants in the FCN2 gene double the chance of bacterial infection in the first year following liver transplant, a risk further increased with the coinheritance of MBL2 gene variants." (PMID 28894916, 2018). "Notably, the risk of bacterial infections was further enhanced if patients possessed both a medium-/high-risk haplotype of FCN2 and a medium-/high-risk genotype of MBL2." (PMID 30868077, 2019). "B acute lymphoblastic leukemia patients were observed to be at a greater risk of bacterial infections and present prolonged episodes of febrile neutropenia if they possessed a medium-/high-risk haplotype for FCN2 of GGATG, GGACG, or AGACG (all haplotypes composed of -986/-602/-4/+6359/+6424)." (PMID 30868077, 2019). "Thus ficolin-2 insufficiencies might play an advantageous role in the protection against Leishmania as do MBL2 polymorphisms for bacterial infections." (PMID 22457818, 2012).
infectious disease (5 papers, 2011 to 2025). A disorder directly resulting from the presence and activity of a microbial, viral, or parasitic agent in humans. "FCN2 encodes the human ficolins that bind to specific pathogen-associated molecular patterns and show great potential in innate immunity to infectious diseases." (PMID 39739972, 2024). "Low Ficolin-2 serum levels and FCN2 gene polymorphisms were associated to several infectious diseases such as respiratory infections in children and invasive pneumococcal disease in adults." (PMID 22140517, 2011). "Ficolin-2 serum levels and FCN2 single nucleotide polymorphisms were associated to several infectious diseases." (PMID 22140517, 2011). "Human ficolin-2 (ficolin-2/P35) is a lectin complement pathway activator that is present in normal human plasma and is associated with infectious diseases; however, little is known regarding the roles and mechanisms of ficolin-2 during Mycobacterium tuberculosis (Mtb) infection." (PMID 24040095, 2013). "SNPs in the FCN2 gene have been reported in TB and other diseases, indicating that FCN2 is involved in infectious diseases." (PMID 26379154, 2015).
tumor (5 papers, 2013 to 2022). "To confirm the role of FCN2 in regulating LIHC immunity, we analyzed the correlation between FCN2 and the tumor microenvironment (TME) immunological signatures." (PMID 36425563, 2022). "We used the GEPIA database to investigate the relationship between FCN2 expression and immune cell biomarkers in HCC in order to learn more about the role of FCN2 in tumor immunity." (PMID 36425563, 2022). "RNAseq (transcriptome gene sequencing technology) and Affymetrix were used for further verification, and the results showed that tumor type was the main factor affecting the transcription level of FCN2." (PMID 36425563, 2022). "The nomogram included data on the tumor status, T stage, and FCN2 expression and was based on a Cox proportional hazards regression model." (PMID 36425563, 2022). "Affymetrix analysis exhibited the expression of FCN2 mRNA in all tumor cell lines to be above 3.2." (PMID 36425563, 2022). "We then looked at the relationship between FCN2 expression and immune infiltration in HCC and found that the expression of FCN2 was positively linked to the number of neutrophils, eosinophils, NK cells, Tcm, and DCs infiltrating the tumor." (PMID 36425563, 2022). "The expression of FCN2 mRNA in various tumor tissues was investigated." (PMID 36425563, 2022). "To explore whether there is a link between FCN2 expression and tumor immune response, we conducted a single-sample gene set enrichment analysis (ssGSEA) to evaluate the immune cell infiltration in HCC tissues with various FCN2 expression levels." (PMID 36425563, 2022). "At the immune level, FCN2 may suppress the tumor immune response of HCC by upregulating the entry of neutrophils, eosinophils, NK cells, Tcm, and DCs and downregulating the entry of Th2 into tumors." (PMID 36425563, 2022). "Based on our findings, FCN2 may play a role in modulating the tumor immune response." (PMID 36425563, 2022). "However, estimation of the expression of either FCN2 or FCN3 gene does not distinguish between patients with less or more advanced disease stage, particular histological types or tumour grade, at least with the relatively small number of samples investigated here." (PMID 23744477, 2013).
inflammation (1 paper, 2014). Aberrant reaction of the microcirculation characterized by movement of fluid and leukocytes from the blood into extravascular tissues. "Our results support the hypothesis that endothelial cell dysfunction may induce pulmonary inflammation and fibrosis and that this process might be partially mediated by MBL and ficolin-2." (PMID 25403109, 2014).
respiratory disorders (1 paper, 2023). "Several reports evidenced association of low ficolin-2 concentration with diseases of the respiratory system." (PMID 36733481, 2023). "Determination of ficolin-2 concentration in cord serum may be considered a new early prognostic factor in RDS development, helpful to distinguish RDS from other prematurity-associated respiratory disorders and thus facilitating the choice of appropriate treatment." (PMID 36733481, 2023).
FCN2 also shares sentences with these, for which no sentence is quoted: Arthritis (2 papers); chronic rheumatic heart disease (2); dementia (2); multiple myeloma (2); non-alcoholic fatty liver disease (2); rheumatic fever (2); Thrombocytopenia (2); viral infection (2); acute liver failure (1); advanced heart failure (1); age-related macular degeneration (1); allergic asthma (1); allergic disease (1); anaemia (1); B cell lymphoma (1); calcinosis (1); cervical cancer (1); chronic obstructive pulmonary disease (1); cognitive decline (1); common variable immunodeficiency (1); complement deficiencies (1); dental caries (1); diabetic nephropathy (1); diffuse large B-cell lymphoma (1); endometrial cancer (1); endothelial dysfunction (1); fungal infection (1); gastric cancer (1); glomerulopathies (1); hyperglycaemia (1).
A further 22 diseases each share a sentence with FCN2 in 1 paper.